PRNP (prion protein (Kanno blood group))
Diseases named in the same sentence as PRNP in open-access papers (continued):
Sharing a sentence is not in itself a finding about the gene and the disease.
prion disease (continued). "Multiple mutations and polymorphisms of PRNP have been described in different animal species and some of them demonstrated an important effect on prion disease susceptibility/resistance." (PMID 33801117, 2021). "In this review article, we will focus on the known cross-talk between classic prion diseases, associated with mammalian PRNP protein with miRNAs." (PMID 34209482, 2021). "We report here that the biallelic R136S PRNP mutation causes inherited human prion disease with early onset of symptoms (30s–40s)." (PMID 34663460, 2021). "FFI, similar to fCJD, is a hereditary prion disease due to a mutation at codon 178 of the PRNP gene that substitutes asparagine with aspartic acid (D178N) and is autosomal dominant." (PMID 34960722, 2021). "In several forms of genetic prion disease, for example those associated with the E200K PRNP mutation, the clinical disease manifestations, PrPres WB signature and tissue PrPres distributions are similar to that in sCJD." (PMID 33532912, 2021). "Codon 129 in the human PRNP has been described as a key polymorphism influencing susceptibility to prion diseases, and more particularly, to the BSE agent." (PMID 33668798, 2021). "The term prion refers to the proteinaceous agent causing prion diseases, now known to be PrPSc, the pathological isoform of the cellular prion protein PrPC, which is encoded by the PRNP gene." (PMID 33450819, 2021). "The biallelic R136S substitution is a rare PRNP mutation that induces inherited human prion disease presenting with early-onset dementia and motor impairment and neuropathological and molecular features consistent with GSS." (PMID 34663460, 2021). "Genetic prion diseases represent ~ 15% of human prion diseases and are caused by genetic variants in the PRNP gene, located on the chromosome 20." (PMID 34663460, 2021). "In humans, prion strain variation and the polymorphic codon 129 of PRNP are two of the major biological determinants of the clinicopathological phenotype of the disease and an individual’s susceptibility to develop prion diseases." (PMID 34413769, 2021). "Genetic prion disease (gPrD) accounts for 10–15% of prion diseases and is caused by pathogenic sequence variations in the prion protein gene (PRNP)." (PMID 34578375, 2021). "Prion diseases in humans can be caused by inherited mutations in the PRNP gene, the most common mutation causing familial CJD is E200K." (PMID 34960722, 2021). "It is equivalent to codon 113 in human PRNP, located in the HC domain where other mutations are responsible for heritable prion disease." (PMID 33668798, 2021). "Human genetic prion diseases are caused by mutations in the prion protein (PrP) encoding gene PRNP which is located on the short arm of chromosome 20." (PMID 32501129, 2020). "In the case of sporadic prion disease, the explanations tendered to account for this etiology include spontaneous somatic mutations in the prion gene PRNP or rare stochastic conformational changes to create misfolded proteins." (PMID 32219515, 2020). "Since polymorphism of the PRNP gene has been associated with the susceptibility to prion diseases, we amplified the ORF region of the canine PRNP gene to identify the genetic polymorphism of this gene." (PMID 32532135, 2020). "Inherited prion diseases are caused by autosomal dominant coding mutations in the human prion protein (PrP) gene (PRNP) and account for about 15% of human prion disease cases worldwide." (PMID 32516343, 2020). "In previous studies, genetic polymorphisms of the prion protein gene (PRNP) were associated with the susceptibility of several types of prion diseases." (PMID 32532135, 2020). "Various rodent models of prion diseases aid in therapeutic progression with accurate expressions of the disease phenotype; direct intracerebral inoculation of PRNP or mutated PRNP transgenic mice lines have all been produced." (PMID 32825239, 2020).
prion disease (continued). "Despite many studies on prion diseases, the role of pathogenic mutations on the generation of a misfolded PrPc and how pathogenic PRNP mutations are involved in prion diseases has yet to be resolved." (PMID 32992764, 2020). "Genetic Creutzfeldt–Jakob disease (gCJD) is characterized by mutations in the PRNP gene and represents approximately 10–15% of the human prion diseases." (PMID 32501129, 2020). "We investigated miRNA alterations in a Tg501 mouse model of prion diseases that expresses a transgene encoding the goat prion protein (PRNP)." (PMID 32549330, 2020). "A number of mutations in the PRNP gene result in fatal neurodegenerative diseases whose phenotypes overlap with those of sporadic prion diseases." (PMID 32584805, 2020). "Prion diseases have been reported in several mammals, and genetic polymorphisms of the prion protein gene (PRNP) play an essential role in the vulnerability of prion diseases." (PMID 33374431, 2020). "More than 60 point or insertion mutations in the PRNP have been associated with human genetic prion diseases." (PMID 32501129, 2020). "Recently, cerebral organoids derived from human iPSCs were established for the first time as a 3D model to study genetic prion diseases in individuals with a predisposition caused by the mutation PRNP-Y218N." (PMID 32528949, 2020). "The inherited prion diseases (IPD) are caused by autosomal dominant inheritance of mutations in the PRNP gene, which in total are responsible for 10–15% of the incidence of human prion disease." (PMID 31734530, 2019). "Up to date, at least 30 pathogenic mutations of the PRNP worldwide have led to familial prion diseases." (PMID 31122137, 2019). "Genetic forms of prion diseases are associated with mutations in the human prion protein gene (PRNP) and comprise familial CJD (fCJD), Gerstmann–Straussler–Scheinker (GSS) syndrome, fatal familial insomnia (FFI) and prion protein cerebral amyloid angiopathy." (PMID 31349611, 2019). "Lastly, we surveyed SNPs of the PRNP gene in prion disease-susceptible species (humans, sheep, goats, and cattle) and prion disease-resistant species (horses and chickens)." (PMID 31795947, 2019). "An important aspect of human prion diseases is the presence of a large number of mutations in the human PrP gene (PRNP) that segregate with familial CJD, Gerstmann-Sträussler-Scheinker (GSS) disease or fatal familial insomnia." (PMID 30646817, 2019). "From our surveillance data of human prion diseases since 2006, about 150 cases of genetic prion diseases have been identified, which contain 15 different subtypes of PRNP mutations, which accounts about 10% of all referring human prion diseases." (PMID 30755683, 2019). "Approximately 90% of human prion diseases are sporadic, 10% are associated with pathogenic mutations in PRNP gene, and 1% is caused by zoonotic or iatrogenic prion infection." (PMID 29867164, 2018). "The polymorphisms of the prion protein (PRNP) gene, which encodes normal prion proteins (PrP), are known to be involved in the susceptibility of prion diseases." (PMID 30359416, 2018). "While obtaining blood samples from patients with sCJD prior to the onset of symptoms is rarely possible, carriers of PRNP mutations causing inherited forms of prion disease can provide blood samples in the presymptomatic phase." (PMID 29487167, 2018). "The aim of this work was to study the PRNP gene of the different species of wild ruminants of the Northeast area of Spain in order to evaluate their status of resistance or susceptibility to prion diseases." (PMID 29631620, 2018). "Several polymorphisms in the paralogs of the PRNP gene have been shown to be associated with prion disease susceptibility." (PMID 30359416, 2018). "Inherited prion diseases (IPDs) comprise 10%–15% of the total annual incidence and are associated with coding mutations in the prion protein gene (PRNP)." (PMID 29861043, 2018).
prion disease (continued). "The elk ML polymorphism at position 132 of Prnp is of particular interest because it corresponds to the methionine–valine (MV) PRNP codon 129 polymorphism in humans, which is itself a major genetic susceptibility factor associated with human prion disease." (PMID 30014840, 2018). "Two polymorphisms of codons 129 and 219 in the human PRNP gene are considered crucial factors in determining susceptibility to human prion diseases." (PMID 30359416, 2018). "For example, the prion gene (PRNP) affects susceptibility to spongiform encephalopathies such as chronic wasting disease in cervids." (PMID 29479424, 2018). "Fatal Familial Insomnia (FFI) is a genetic prion disease caused by a point mutation in the prion protein gene (PRNP) characterized by prominent thalamic atrophy, diffuse astrogliosis and moderate deposition of PrPSc in the brain." (PMID 28387370, 2017). "Inherited prion disease occurs due to germline mutations in PRNP that predispose individuals to CJD, Gerstmann-Straussler-Scheinker Disease or Fatal Familial Insomnia." (PMID 28431525, 2017). "Polymorphism at codon 129 of the human PrP gene (PRNP), where methionine (Met) or valine (Val) can be encoded, strongly affects susceptibility to human prion diseases." (PMID 28820136, 2017). "During the last two decades several transgenic models have been generated by integrating mutations in the PRNP which are linked to different human genetic prion diseases." (PMID 28851967, 2017). "The heterozygous c.385A>G p.Met129Val in the PRNP gene has been described as a risk factor for prion disease, early-onset Alzheimer disease and primary progressive aphasia." (PMID 28076385, 2017). "A large set of human genomic data was analyzed to quantify the penetrance of variants of the human PrPC gene (PRNP) in prion disease." (PMID 28464931, 2017). "Genetic prion diseases are dominantly inherited neurodegenerative disorders linked to mutations in the PRNP gene encoding the cellular prion protein (PrPC), on chromosome 20." (PMID 26864450, 2016). "Similar biased sequences also exist in the PRNP protein, which is associated with prion disease, in α-synuclein, which is associated with Parkinson disease and other disease-related proteins." (PMID 27226608, 2016). "For example, molecular classification of human prion disease is based on the Western blot pattern of PrPres (i.e., PK-resistant PrP) together with the codon 129 polymorphism of the PRNP." (PMID 26848654, 2016). "Inherited prion diseases (IPDs), including genetic Creutzfeldt-Jakob disease (gCJD), account for 10–15% of cases of prion diseases and are associated with several pathogenic mutations, including P102L, V180I, and E200K, in the prion protein gene (PRNP)." (PMID 27341347, 2016). "This study claimed the first non-PRNP locus to be highly significantly associated with prion disease in genomic studies." (PMID 27055460, 2016). "Among the top 15 pathways, the pathway most significantly was associated with prion disease (p < 1e-16) was found to be influenced by a single miRNA, miR-130b-3p, which was predicted to target a single transcript PRNP (prion protein gene)." (PMID 25807141, 2015). "Genetic prion diseases are linked to point mutations and insertions in the PRNP gene encoding PrPC on chromosome 20." (PMID 25880443, 2015). "Beyond prion infections, the clinical onset of genetic prion diseases varies greatly, even when the effects of a common PRNP codon 129 polymorphism on the disease chromosome and on the non-mutated chromosome are excluded from the analyses." (PMID 25661904, 2015). "Currently, more than 55 dominant mutations in the PRNP gene that are directly associated with human genetic prion diseases have been described." (PMID 26488179, 2015). "Inherited prion disease (IPD) is caused by autosomal-dominant pathogenic mutations in the human prion protein (PrP) gene (PRNP)." (PMID 26135918, 2015).
prion disease (continued). "PRNP variant alleles with insertions, or deletions, of octapeptide repeat units result in prion disease in humans." (PMID 24555712, 2014). "Genetic prion disease due to single point mutations in the gene for the prion protein, PRNP, can lead to vastly different disease phenotypes, including the area of the brain in which infection proliferates to the greatest extent." (PMID 26784872, 2014). "Although defined by clinico-pathological criteria, different subtypes of human prion disease can be classified using these PrPres molecular profiles in conjunction with the presence of mutations and polymorphisms in the prion protein gene (PRNP)." (PMID 25331173, 2014). "We describe a case of severe, rapidly progressive neurological WD in a patient who was found to carry heterozygous allelic variants in the two genes (ATP7B and PRNP) that have been linked to WD and prion disease, respectively." (PMID 24555712, 2014). "The different truncating mutations in PRNP appear to have some common features namely: prolonged clinical courses, atypical for prion diseases, severe neurofibrillary tangle pathology, and high levels of cerebral amyloidosis." (PMID 24958194, 2014). "Several mutations in the PrP gene (PRNP) account for the genetic or familial form of human prion disease, in which the conversion of PrPC into PrPSc is thought to occur spontaneously, triggered by the mutation." (PMID 24454379, 2013). "Familial prion diseases account for about 5–15% of human TSEs and a number of mutations within the prion protein gene (PRNP) are disease associated." (PMID 24228054, 2013). "In conclusion, the presence or amount of CSF biomarkers in patients with genetic prion disease varies with the PRNP mutation." (PMID 23555862, 2013). "While point mutations are responsible for genetic prion diseases, some polymorphisms in PRNP influence the etiology and neuropathology of the disease." (PMID 23966072, 2013). "Sheep scrapie represents a unique diversity of prion disease agents in a range of susceptible PRNP genotypes." (PMID 23153009, 2012). "The PRNP gene determines both susceptibility and phenotypes of prion diseases in humans, with point mutations leading to a specific pathological phenotype." (PMID 23372423, 2012). "Similar associations exist in other species and are used to assign a prion disease risk to a specific PRNP genotype." (PMID 23236380, 2012). "Present knowledge supports the notion that the host’s PrPC (encoded by prion protein gene, PRNP) plays a central role in prion diseases since its expression is absolutely required for disease progression." (PMID 23071594, 2012). "Incubation time and susceptibility of animals to natural prion disease are affected by sequence variations in the prion gene (PRNP)." (PMID 22916207, 2012). "Although polymorphisms of PRNP, the gene encoding prion protein, are known as a determinant affecting prion disease susceptibility, other genes also influence prion incubation time." (PMID 21838916, 2011). "A large number of point mutations in the PRNP coding region have also been linked to familial prion diseases in humans." (PMID 22028931, 2011). "The PRNP associated resistance/susceptibility for prion disease is likely to coexist with other genes modulating its effect." (PMID 21838916, 2011). "A large number of point mutations in the PRNP coding region have been linked to inherited prion diseases with diverse phenotypes: familial CJD (fCJD), GSS, fatal familial insomnia (FFI), and mixed phenotypes." (PMID 22028931, 2011). "The inherited forms of prion diseases base on different mutations in the prion protein gene (PRNP) on chromosome 20, which are associated with various clinical phenotypes and responsible for about 10-15% of prion disorders." (PMID 21689433, 2011). "Genetic variations in the prion protein gene (PRNP) are linked to the occurrence of transmissible spongiform encephalopathies (TSEs) also called prion diseases in humans, sheep and mice." (PMID 21611160, 2011).
prion disease (continued). "These pathogenic PRNP mutations are believed to cause prion diseases by rendering the corresponding mutant PrP protein more prone to adopting a prion-associated conformation." (PMID 22028931, 2011). "A loss of PRNP functionality was largely proposed as one of the main causes of a prion disease physiopathology." (PMID 21483752, 2011). "Inherited prion disease accounts for ∼15% of human prion disease and is caused by mutations in the prion gene (PRNP)." (PMID 21151910, 2010). "This represents the first case of BSE with a potentially pathogenic mutation within the bovine PRNP gene, and experiments are underway to determine the potential importance of this mutation in the development of prion disease in cattle." (PMID 20498835, 2010). "How pathogenic mutations in PRNP cause prion disease has yet to be resolved; however, in most cases the mutation is thought to lead to an increased tendency of PrPC to form PrPSc." (PMID 20880036, 2010). "Inherited prion diseases (IPDs) are fatal neurodegenerative disorders caused by autosomal-dominant mutations in the human PrP gene (PRNP), and constitute about 15 % of all human prion disease." (PMID 19218199, 2009). "For exposure to prion disease to shape PRNP allele frequency in susceptible populations, salient parameters will be the presence of a disease-related physiological deficit at the age when mating partners are selected, and exposure at an endemic level." (PMID 19657386, 2009). "The PRNP locus was strongly associated with risk across several markers and all categories of prion disease (best single SNP [single nucleotide polymorphism] association in vCJD p=2·5×10−17; best haplotypic association in vCJD p=1×10−24)." (PMID 19081515, 2009). "Recently, there has been growing concern about several polymorphisms outside the ORF of PRNP, as there is evidence that levels of PRNP expression influence incubation time and the susceptibility to prion diseases." (PMID 19351416, 2009). "About 15% of prion disease cases are associated with mutations in the PRNP gene and ~85% of the cases are classified as sporadic." (PMID 18366654, 2008). "In this study, we use a model system created to investigate some aspects of an inherited form of prion disease that results from insertional mutations in PRNP to cause diseases such as GSS and CJD." (PMID 18366654, 2008). "About 10%–15% of human prion diseases are inherited in an autosomal, dominant fashion and in all cases a mutation in the coding region of the human prion protein gene (PRNP) has been found." (PMID 18478114, 2008). "Several different mutations in PRNP are associated with prion diseases, but the mechanisms by which the various mutations cause disease are not always clearly understood." (PMID 18366654, 2008). "In the majority of human cases, prion diseases arise sporadically with the spontaneous conversion of PrPC into PrPSc, while a smaller percentage is inherited, associated with mutations in the open reading frame of PRNP." (PMID 38918277, 2025). "Polymorphisms of the PRNP gene encoding PrPC are a major determinant of host susceptibility to prion diseases and may also be a factor influencing the establishment of subclinical infections." (PMID 40116281, 2025). "The PRNP E200K variant is generally believed to cause genetic prion disease with high penetrance, based on its segregation with disease in many multigenerational families, the high proportion of cases with a positive family history, and its dramatic enrichment in prion disease cases over controls." (PMID 41256127, 2025). "Given the economic significance of sheep farming for Kazakhstan and the potential risks of cross-border spread of prion diseases, conducting large-scale screening of PRNP gene polymorphisms in local breeds, as well as implementing monitoring programs for small ruminants, is highly relevant." (PMID 40933525, 2025).